MIR4313 (microRNA 4313)
Synonyms: hsa-mir-4313
Gene: MicroRNA gene on chromosome 15 (75,762,215 to 75,762,315, reverse strand). Ensembl gene ENSG00000284385.
Homologues: Orthologues: chimpanzee MIR4313 (100% identical).